FEN1 (flap structure-specific endonuclease 1)
Diseases named in the same sentence as FEN1 in open-access papers (continued):
Sharing a sentence is not in itself a finding about the gene and the disease.
acute lymphoblastic leukemia (1 paper, 2022). Leukemia with an acute onset, characterized by the presence of lymphoblasts in the bone marrow and the peripheral blood. "The presence of the FEN1 mutant rs174538 A allele may serve as a novel detectable and predictive biomarker for childhood acute lymphoblastic leukemia (ALL)." (PMID 35883563, 2022).
B-cell lymphomas (1 paper, 2020). "In agreement, female mice with a compound Fen1 mutation in the nuclease domain developed B-cell lymphomas originating from GC B cells." (PMID 32547565, 2020). "A considerable proportion (17%) of Fen1+/− mice developed B-cell lymphomas." (PMID 32547565, 2020).
benign breast diseases (1 paper, 2021). "Serum FEN1 levels were significantly higher in BC patients than in patients with benign breast diseases and healthy individuals." (PMID 34277392, 2021).
bone sarcoma (1 paper, 2025). A sarcoma that arises from the bone. "Using publicly available datasets to assess gene dependency across cell lines, we observed that bone was the most sensitive tissue, and within bone sarcoma lines, EWS models were highly dependent on FEN1." (PMID 41359388, 2025).
cholelithiasis (1 paper, 2015). The presence of crystallized deposits forming in the gallbladder or biliary tree, primarily composed of cholesterol, bilirubin, and bile. "Significant interactions between FEN1 -69G > A (GA or GG) and 4150G > T (GT or GG) or between these genetic factors and cholelithiasis were identified." (PMID 26668074, 2015).
colorectal tumor (1 paper, 2023). "In the current study, we investigated the potential causal protective locus rs4246215 G>T in FEN1, a locus associated with DNA replication, and its effect on the colorectal tumor immune microenvironment involved in tumorigenesis." (PMID 38111199, 2023). "Importantly, we identified basophils and eosinophils that both exhibited a significantly decreased infiltration in colorectal tumors, and were regulated by rs4246215 through causal pathways involving both FEN1 and DNA replication." (PMID 38111199, 2023). "Our findings revealed that both DNA replication activity and the flap structure-specific endonuclease 1 (FEN1) gene were significantly enriched in colorectal tumor tissues, compared with normal tissues." (PMID 38111199, 2023). "Subsequent multiplex immunofluorescence staining confirmed the high expression of FEN1 in colorectal tumors." (PMID 38111199, 2023). "Our results confirmed the spatial distribution of immune cells and tumor cells, and revealed differential infiltration of basophils, eosinophils, and FEN1 in colorectal tumors, compared with normal tissues." (PMID 38111199, 2023). "Intriguingly, we observed that rs4246215 led to a downregulation of FEN1 expression in colorectal tumors, while it conversely upregulated FEN1 expression in normal tissues." (PMID 38111199, 2023). "We then assessed infiltrating immune cells in colorectal tumors and adjacient normal tissues to determine whether FEN1 and DNA replication are involved in colorectal tumorigenesis via the immune pathway (available online)." (PMID 38111199, 2023).
COVID-19 (1 paper, 2024). A disease caused by infection with severe acute respiratory syndrome coronavirus 2. "Fen1, involved in critical DNA synthesis and repair mechanisms, was overexpressed in our COVID-19 cohort." (PMID 38760690, 2024).
cystic fibrosis (1 paper, 2025). Autosomal recessive disorder caused by pathogenic variants in the CFTR gene (cystic fibrosis transmembrane conductance regulator), which encodes a chloride and bicarbonate channel expressed in epithelial cells, and follow the diagnosis criteria. "Specifically, we fused FEN1, EXO1, and a truncated EXO1 variant (HEX-N2 domain) to the PEmax using either 16-amino acid or 4-amino acid linkers as part of our therapeutic development strategy for cystic fibrosis treatment." (PMID 40869263, 2025).
depression (1 paper, 2023). "Interestingly, our previous study investigated one SNP located in FEN1, but it did not influence the incidence of depression." (PMID 37834200, 2023).
gallstones (1 paper, 2015). Solid crystalline precipitates in the biliary tract, usually formed in the gallbladder, resulting in the condition of cholelithiasis. "This association was not affected by adjusting other factors (age, sex and gallstone) via regression analysis (ORadjust = 1.74, 95% CI = 1.02–2.64 for the FEN1-69G > A GA genotypes; ORadjust = 2.31, 95% CI = 1.32–3.96 for the FEN1-69G > A GG genotypes)." (PMID 26668074, 2015).
gastric tumours (1 paper, 2021). "Overexpression of FEN1 has been reported in previous studies such as in breast, prostate, testis, lung, brain and gastric tumours." (PMID 34117958, 2021).
HCMV infection (1 paper, 2021). "We found FEN1 to be upregulated starting with the early phase of HCMV infection, where viral DNA replication takes place, thereby suggesting a possible involvement of FEN1 in viral DNA replication." (PMID 33770148, 2021). "To make sure that the observed phosphorylation of FEN1 also occurs in the viral context, we next investigated the phosphorylation of endogenous FEN1 during the time course of HCMV infection." (PMID 33770148, 2021). "To obtain further insight how FEN1 acts to promote viral DNA replication, we analyzed the subcellular localization of FEN1 during HCMV infection by utilizing HFFs stably expressing mCherryFEN1." (PMID 33770148, 2021). "Intriguingly, we observed an attenuated accumulation of FEN1 protein levels at 24 and 48 hpi indicating that the presence of IE1 is necessary for an efficient upregulation of FEN1 during HCMV infection (first panel, compare lanes 2 and 4 with 3 and 5)." (PMID 33770148, 2021). "Depletion of FEN1 and inhibition of its enzymatic activity during HCMV infection significantly reduced nascent viral DNA synthesis demonstrating a supportive role for efficient HCMV DNA replication." (PMID 33770148, 2021). "We performed further experiments demonstrating that IE1 and FEN1 are both required for the efficient induction of DSBs during HCMV infection, as indicated by γH2AX." (PMID 33770148, 2021). "In order to analyze the subcellular localization of FEN1 during HCMV infection, we again utilized mCherry- and mCherryFEN1 expressing HFFs." (PMID 33770148, 2021). "We next set out to investigate whether IE1 is required for the increase in FEN1 levels during HCMV infection." (PMID 33770148, 2021). "Furthermore, our results indicate that FEN1 is required for the formation of DSBs during HCMV infection suggesting that IE1 acts as viral activator of FEN1 in order to re-initiate stalled replication forks." (PMID 33770148, 2021). "Moreover, experiments with the protein synthesis inhibitor cycloheximide revealed that IE1 binding increases FEN1 protein stability thereby providing an explanation for IE1-mediated FEN1 upregulation during HCMV infection." (PMID 33770148, 2021). "As we could already demonstrate that IE1 is sufficient for the accumulation of phosphorylated FEN1 species, we asked whether IE1 is also necessary for the increase of phosphorylated FEN1 during HCMV infection." (PMID 33770148, 2021). "As we found FEN1 likewise phosphorylated during HCMV infection, we asked whether IE1 might be necessary for the accumulation of phosphorylated FEN1 species." (PMID 33770148, 2021). "In addition to the enhanced stability of FEN1, an accumulation of phosphorylated FEN1 was detected in the presence of IE1 and during HCMV infection." (PMID 33770148, 2021). "Consistently, a reduced/delayed induction of γH2AX, a sensitive marker for DSBs, was observed during HCMV infection in the absence of FEN1 thereby presumably reflecting a defect in re-initiating stalled viral replication forks." (PMID 33770148, 2021). "In order to confirm that the substance does not alter FEN1 expression but only its enzymatic activity, FEN1 protein levels were analyzed during HCMV infection in the presence of PTPD." (PMID 33770148, 2021). "As phosphorylation of FEN1 is described to stimulate its double strand break (DSB)-generating gap endonuclease activity, we propose that FEN1 might be involved in the induction of γH2AX, a sensitive marker for DSBs, during the late phase of HCMV infection." (PMID 33770148, 2021).
Huntington disease (1 paper, 2016). Huntington disease (HD) is a rare neurodegenerative disorder of the central nervous system characterized by unwanted choreatic movements, behavioral and psychiatric disturbances and dementia. "Disruption of the coordination between Polβ and FEN1 in the processing of the flap structure leads to CAG repeat expansion that results in mutant Huntingtin protein expression in Huntington's disease (HD)." (PMID 26942017, 2016).
keratoconus (1 paper, 2014). A degenerative, structural disorder of the eye, characterized by a cone-shaped protrusion of the cornea. "Distribution of genotypes and alleles of the c.–441G>A (rs174538) and the g.61564299G>T (rs4246215) polymorphisms of the FEN1 gene and the odds ratio (OR) with the 95% confidence interval (95% CI) in patients with keratoconus (KC) and controls." (PMID 25153632, 2014).
lentivirus infection (1 paper, 2020). Virus diseases caused by the Lentivirus genus. "shRNA specifically targeting FEN1 was transfected into HepG2 and Hun7 cells by lentivirus infection, respectively." (PMID 33224879, 2020).
lobular breast cancer (1 paper, 2024). "For instance, the role of the CDH1 gene in lobular breast cancer is well documented, while the FEN1 gene is associated with poor prognoses." (PMID 39335599, 2024).
lung adenoma (1 paper, 2009). A benign, well circumscribed epithelial neoplasm that arises from the bronchus or the lung parenchyma. "Recently, EGFR mutations in the kinase domain (exons 18–21) were also found in 14% of lung adenomas/adenocarcinomas from FEN1 mutant knock-in mice." (PMID 19789704, 2009).
mesothelioma (1 paper, 2018). A usually malignant and aggressive neoplasm of the mesothelium which is often associated with exposure to asbestos. "DRUGSURV search identified 10 already approved drugs targeting FEN1 that could be repositioned to treat mesothelioma." (PMID 30316293, 2018).
metastatic tumors (1 paper, 2023). "Our information is in contradiction with previous studies considering FEN1 as a marker of multiple metastatic tumors and poor prognosis and is viewed as an effective target for tumor resistance treatment." (PMID 37298600, 2023).
microcephaly (1 paper, 2023). A congenital or acquired developmental disorder in which the circumference of the head is smaller than normal for the person's age and sex. "According to GO analysis, these genes are associated with either abnormal hematopoiesis (Aurkb, Fen1, Hrob, Kif20a, Rad51ap1 and Tsr2) or microcephaly (Casc5, Hmgb3, Ncaph and Wdr62), or both (Fanca and Trip13)." (PMID 37661832, 2023).
multiple myeloma (1 paper, 2024). "In the application of DrugFormer to the scRNA‐seq data of multiple myeloma, we unveiled a specific cancer cell state exhibiting stronger drug resistance while presenting elevated expressions of FEN1, RBX1, and COX8A." (PMID 39206872, 2024).
myelocytic leukemia (1 paper, 2021). "In pro-myelocytic leukemia cells (HL-60), FEN1 gene expression was shown to be higher during the mitotic phase compared to the resting phase of the cell cycle and FEN1 expression markedly decreased upon induction of terminal differentiation in cells." (PMID 33919707, 2021).
Obesity (1 paper, 2024). Accumulation of substantial excess body fat. "TNF-α downregulated some of the DNA damage repair genes, which are also altered by obesity: PARP1 (−49.3%, P = 0.008), BLM (−46.9%, P = 0.02), FEN1 (−25.5%, P = 0.04), and PCNA (−38.0%, P = 0.008), but did not affect HDAC1 and Ku70 gene expression." (PMID 39092995, 2024).
prostate tumour (1 paper, 2023). "This indicated that AR knockdown further enhanced the inhibitory effect of DTX on prostate tumour growth, while FEN1 overexpression weakened this enhancement." (PMID 37326412, 2023). "In vivo experiments showed that overexpression of FEN1 significantly increased tumour growth and weakened the inhibitory effect of DTX on prostate tumour growth, while AR knockdown enhance the sensitivity of DTX to prostate tumour." (PMID 37326412, 2023).
psoriasis (1 paper, 2023). An autoimmune condition characterized by red, well-delineated plaques with silvery scales that are usually on the extensor surfaces and scalp. "In our study, PTG1, HMMR, PBK, FEN1, DEPDC1 may be some psoriasis-related genes in IL-17A treating of psoriasis." (PMID 37029373, 2023).
Telangiectasia (1 paper, 2023). Telangiectasias refer to small dilated blood vessels located near the surface of the skin or mucous membranes, measuring between 0.5 and 1 millimeter in diameter. "Notably, the PCNA S228I mutation impairs FEN1 and LIG1 interactions and results in clinical features, including short stature, hearing loss, premature aging, telangiectasia, neurodegeneration, and photosensitivity in humans." (PMID 37205694, 2023).
thyroid carcinomas (1 paper, 2019). "Results suggested that the expression levels of hub genes, TOP2A, TYMS, FEN1, and PRC1, were also upregulated in at least one histological subtype of thyroid carcinoma." (PMID 30774662, 2019). "High expression of TOP2A, TYMS, FEN1, PRC1, or UBE2C gene significantly decreased disease-free survival of patients with other thyroid carcinomas." (PMID 30774662, 2019). "TCGA data suggested that the expression levels of TOP2A, TYMS, FEN1, and PRC1 genes were also upregulated in other histological subtypes of thyroid carcinoma." (PMID 30774662, 2019). "Survival analysis indicated that high expression of TOP2A, TYMS, FEN1, PRC1, or UBE2C gene significantly decreased disease-free survival of patients with other thyroid carcinomas." (PMID 30774662, 2019). "Further survival analysis showed that high expression of TOP2A, TYMS, FEN1, PRC1, or UBE2C gene significantly decreased disease-free survival of patients with other thyroid carcinomas." (PMID 30774662, 2019).
Xeroderma pigmentosum complementation group G (1 paper, 2017). Xeroderma pigmentosum complementation group G (XPG) is an extremely rare subtype of xeroderma pigmentosum (XP; see this term), a rare photodermatosis predisposing to skin cancers. "Moreover, FEN1 and the NER protein XPG (xeroderma pigmentosum complementation group G) show homology in the DNA‐binding domain, suggesting that FEN1 may support XPG function in NER." (PMID 28371273, 2017).
cancer (128 papers, 2008 to 2026). A tumor composed of atypical neoplastic, often pleomorphic cells that invade other tissues. "Fen1 is thus inevitable to sustain genomic stability and integrity, and the association of Fen1 mutation with various human cancers has also been reported." (PMID 40685548, 2025). "XPF knockout or inhibition results in the accumulation of 3’ flaps in human cancer cells, particularly under FEN1 deficient of inhibited conditions." (PMID 41279254, 2025). "The FEN1-E160D mutation in mice induces autoimmunity, chronic inflammation, and cancers, followed by the initiation and progression of cancer." (PMID 40685548, 2025). "In our present study, we have described the crucial role of Fen1 in avoiding replication fork arrest as well as DNA damage upon alovudine treatment, thus implementing alovudine as a possible therapeutic drug for Fen1 deficient cancers." (PMID 40685548, 2025). "SNHG16 can act as an endogenous sponge for miR-140-5p and increase flap endonuclease 1 (FeN1), an oncogene associated with many cancers." (PMID 40556662, 2025). "Here, we report that 3’ flaps frequently form in various human cancer cells, and that FEN1 deficiency significantly enhances 3’ flap levels." (PMID 41279254, 2025). "FEN1 is an overexpressed gene in various cancers and has been linked to poor prognosis due to its role as a senescence-related gene in tumor tissues." (PMID 40612863, 2025). "Consistently, XPF inhibition or knockout resulted in the accumulation of 3’ flaps and SSBs on newly synthesized DNA, especially in FEN1 deficient MEFs or FEN1 inhibited human cancer cells such as HCC827 or MDA-MB-231." (PMID 41279254, 2025). "FEN1 (Flap endonuclease 1) is crucial in DNA replication and repair, and its overexpression is linked to poor prognosis in various cancers, indicating its potential as a target for cancer therapy." (PMID 38962012, 2024). "In contrast, overexpression of FEN1 promotes mutations and genomic instability, which are characteristics of cancer." (PMID 38396787, 2024). "In combination with Olaparib, the inhibition of FEN1 leads to increased susceptibility, indicating the gene’s synthetic lethality in HR-deficient cancer cells." (PMID 37508568, 2023). "It was documented that dysregulation of expression or mutation in FEN1 in normal cells leads to provoking various diseases, such as cancers." (PMID 37298600, 2023). "FEN1 mRNA overexpression was also significantly associated with high-grade, ER-negative, PR-negative, triple-negative breast cancer and poor cancer-specific survival." (PMID 37762489, 2023). "FEN1 is highly expressed in several human cancer cells and associated with an increased tumor grade and aggressiveness." (PMID 36829835, 2023). "Recent studies have found that the FEN1-specific inhibitor Compound #8 is abnormally sensitive to cancers with BRCA1 and BRCA2 deficiencies." (PMID 35883563, 2022). "FEN1-mediated HR replaces NHEJ in enabling the progression of stressed replication forks in DNA-PKcs-deficient cancers and is related to the malignancy of tumors and resistance to clinical treatment." (PMID 35414100, 2022). "In some cases, overexpression of FEN1 can enhance cancer susceptibility, accelerate malignancy progression, and reduce cancerous patient survival." (PMID 35883563, 2022). "Abnormal expression or mutation of FEN1 in cells can cause a series of pathological responses, leading to various diseases, including cancers." (PMID 35883563, 2022). "Pharmaceutical development of FEN1 inhibitors is likely to have a clinical impact on BRCA deficient cancers." (PMID 33919707, 2021). "FEN1 has been observed overexpressed in a broad spectrum of cancers and was previously associated with PCNA-dependent genetic instability and DNA damage." (PMID 34616685, 2021). "FEN1 mutations play a role in some autoimmune diseases, chronic inflammatory conditions and cancer predisposition." (PMID 34117958, 2021).